MAPK3 (mitogen-activated protein kinase 3)
Diseases named in the same sentence as MAPK3 in open-access papers (continued):
Sharing a sentence is not in itself a finding about the gene and the disease.
cardiac hypertrophy (220 papers, 2009 to 2026). "In support of our findings, a mouse model with deletion of MAPK3/MAPK1 genes developed cardiac hypertrophy and ventricular dilation followed by reduced ventricular performance." (PMID 37429843, 2023). "It has been suggested that MAPK3 induces cardiac hypertrophy in response to pathological injury in the heart." (PMID 35145551, 2022). "In this present study, we predicted that AKT1 and MAPK3 might be the key targets of the active compound naringenin in Chenopodium during the prescreening process to regulate myocardial hypertrophy." (PMID 35281609, 2022).
colon carcinoma (220 papers, 2005 to 2025). "Interactions between the STK11 (LKB1)-AMPK pathway and the MAPK3/1 pathway in human cancer cells including colon cancer cells have been documented." (PMID 20808308, 2010). "AMP-activated protein kinase is rapidly activated by cisplatin and suppresses an apoptotic signal via MAPK3/1 in colon cancer cells." (PMID 20808308, 2010). "In colon cancer cells, AMPK potentially inhibits the MAPK3/1 pathway; inhibition of AMPK by expressing a dominant-negative form potentiates MAPK3/1 activation under glucose deprivation." (PMID 20808308, 2010). "Our gene expression analysis also shows differential expression for some of the genes of the MAPK pathway, such as Mitogen-Activated Protein Kinase 3 (MAPK3), Mitogen-Activated Protein Kinase 12 (MAPK12), which were upregulated and downregulated, respectively, in the AA colon cancer cell lines." (PMID 36531053, 2022).
hepatocellular carcinoma (217 papers, 2007 to 2025). A malignant tumor that arises from hepatocytes. "For example, ALDH1A1 (stress response) and MAPK3 (cell proliferation) are targets of the HGF/MET signaling pathway which has been associated with tumor metastasis and poor prognosis in human hepatocellular carcinomas." (PMID 17900369, 2007). "Proteins in the first group, including AKT1, PIK3CA, MAPK3, MAPK2K1, and MAPK14, have been verified to be involved in the apoptosis of hepatocellular carcinoma cells." (PMID 36817123, 2023).
ovarian carcinoma (211 papers, 2006 to 2025). A malignant neoplasm originating from the surface ovarian epithelium. "However, low doses of BPA (under 1μM) activates rapidly MAPK3/1 signalling in human placental and ovarian cancer cells." (PMID 32059612, 2020). "Although BOTs are not entirely recognized as malignant tumors and are not seen as a necessary process of transformation into ovarian cancer, in this study, we found some biomarkers related to EMTs, such as IL6, AKT1, MAPK3, SRC, TWIST1, and TGFB1." (PMID 33921111, 2021).
colorectal cancer (203 papers, 2008 to 2026). A primary or metastatic malignant neoplasm that affects the colon or rectum. "In particular, experimental evidence showed that variations in MAPK3 influence colorectal cancer (CRC) risk and survival after diagnosis." (PMID 34671555, 2021). "In contrast, among p-AMPK-positive cases, p-MAPK3/1 expression was significantly associated with superior colorectal cancer-specific survival (adjusted HR 0.55; 95% CI: 0.35–0.86)." (PMID 20808308, 2010). "A study on 135 colorectal cancers has shown that p-MAPK3/1 expression is associated with poor prognosis." (PMID 20808308, 2010). "Our results support an interaction between the AMPK and MAPK3/1 pathways in colorectal cancer cells to modify tumour behaviour." (PMID 20808308, 2010). "Briefly, we found that mmu-miR-688 and mmu-miR-30c-1* targeting Tcf712 and Cdk4 are involved in colorectal and pancreatic cancer, respectively, while the same miRNAs targeting Bad, Mapk10, Mapk3 and Tgfbr1 are involved both in pancreatic as well as colorectal cancer." (PMID 22245972, 2012). "Among p-AMPK-negative cases, p-MAPK3/1 expression was significantly associated with inferior colorectal cancer-specific survival (adjusted HR 1.94; 95% CI: 1.17–3.24; p-MAPK3/1-positive vs negative tumours)." (PMID 20808308, 2010). "Phosphorylated AMPK expression in colorectal cancer is associated with superior prognosis among p-MAPK3/1-positive cases, but not among p-MAPK3/1-negative cases, suggesting a possible interaction between the AMPK and MAPK pathways influencing tumour behaviour." (PMID 20808308, 2010). "Phosphorylated AMPK expression was associated with superior colorectal cancer-specific survival (adjusted HR 0.42; 95% confidence interval (CI), 0.24–0.74) among p-MAPK3/1-positive cases, but not among p-MAPK3/1-negative cases (adjusted HR 1.22; 95% CI: 0.85–1.75)." (PMID 20808308, 2010). "In colorectal cancer cell spheroids, the PpIX-PDT can activate the MAPK1/ERK2 and MAPK3/ERK1 pathway as an adaptative and survival mode to resist the mitochondrial photooxidative damage." (PMID 33552982, 2020). "We found a significant modifying effect of p-MAPK3/1 expression on the relation between p-AMPK expression and mortality (Pinteraction=0.0017 (for colorectal cancer-specific mortality) and Pinteraction=0.0026 (for overall mortality))." (PMID 20808308, 2010). "In contrast to that study (N=135), our study evaluated the expression status of both p-MAPK3/1 and p-AMPK in a much larger cohort of 718 colorectal cancers." (PMID 20808308, 2010). "To test this hypothesis, we utilised a database of 718 stage I–IV colorectal cancers in two prospective cohort studies, and examined the prognostic role of phosphorylated-AMPK expression and modifying effect of MAPK3/1." (PMID 20808308, 2010). "Since the positivity of MAPK3/1 is limited within colorectal cancer specimens, it is therefore explanatory that over-reactivity of AMPK is not a direct predictor of survival outcome among colorectal cancer patients." (PMID 27716618, 2016).
pancreatic cancer (202 papers, 2003 to 2026). "Another genome-wide significant sequence variant, rs7542 (p = 1.689e-11), is located in MAPK3, a protein-coding gene associated with cholangiocarcinoma and pancreatic cancer where smoking play a definite role in, associated with developmental delays and intellectual disabilities." (PMID 37555321, 2023). "2-DG sensitized pancreatic cancer cells and tumors to inhibition of MEK, the kinase immediately upstream of MAPK3 in the RAS-induced kinase activation cascade." (PMID 35887124, 2022). "EGFR has also been shown to be required for tumorigenesis in a K-Ras(G12D) pancreatic cancer model, and ablation of EGFR leads to ∼2-fold reduction of downstream levels of Ras-GTP and phosphorylated ERK (herein referring to ERK1 and ERK2, also known as MAPK3 and MAPK1, respectively)." (PMID 41132131, 2025).
glioma (201 papers, 2009 to 2026). A benign or malignant brain and spinal cord tumor that arises from glial cells (astrocytes, oligodendrocytes, ependymal cells). "MiR-483-5p was significantly down-regulated in gliomas and directly targeted ERK1 (alias MAPK3) transcript." (PMID 26646588, 2016). "Genes negatively correlated with ZNF800, such as MAPK3, may act as tumor suppressors that promote autophagy in glioma cells." (PMID 40644416, 2025). "Tyrosine-specific phosphoproteomic analysis of IL-33+ tumors showed an increase in a number of phospho-peptides derived from STAT3, CDK1, CDK2, FYN, MAPK14, and MAPK3, some that based on amino acid sequence could be attributed to either human glioma or mouse host origin." (PMID 33020472, 2020). "Mitogen-activated protein kinase 3 (MAPK3) mediates the onset, progression, metastasis, drug resistance, and poor prognosis in various malignancies, including glioma, liver, ovarian, thyroid, lung, breast, gastric, and oral cancers." (PMID 37090055, 2023). "By target harvesting, six core genes including AKT1, JUN, ALB, MAPK3, MAPK1, and TNF were screened from a total of 205 targets of luteolin against the glioma network." (PMID 34873410, 2021). "MAPK3 and CX3CL1 were strongly positive; NFE2L2, HSP90AB1, and SUPT20H were moderately positive; and FKBP1B, BIRC5, NPC1, IKBKE, BID, and PTEN were weakly positive in glioma tissue relative to their expression levels in normal tissue." (PMID 33194668, 2020).
diabetes (126 papers, 2005 to 2026). "Based on these findings, it may be inferred that the reported JME phytocompounds could be used for in vitro and in vivo research, with the goal of targeting MAPK3 inhibition for the treatment of obesity-linked diabetes mellitus." (PMID 36716329, 2023). "Diabetes-prone mice's blood glucose levels were reported to be controlled by MAPK3 (ERK1) inhibitor inhibition in hypertrophic 3T3-L1." (PMID 36239103, 2022). "Research on MAPK3 in diabetes and its complications has yielded multiple findings." (PMID 41503916, 2026). "Mapk1, Mapk3, Ikbkb, and Nfkb1 were expressed at higher levels in the diabetic liver injury group." (PMID 40438398, 2025). "Also, it was noted in another research that MAPK3 and MAPK1 were involved in heart failure caused by diabetes." (PMID 36937538, 2023). "Notably, the PI3K-Akt signaling pathway, a critical pathway in diabetes, was enriched with additional key targets, including IL6, HSP90AA1, FN1, MAPK1, AKT1, PIK3R1, and MAPK3." (PMID 40170727, 2025).
cervical carcinoma (97 papers, 2011 to 2026). A carcinoma arising from either the exocervical squamous epithelium or the endocervical glandular epithelium. "For instance, the increase of TRIB3 expression in HeLa cervical carcinoma cells resulted in the inhibition of MAPK14, MAPK3/1 and MAPK8 (JNK) activities via binding to MAPK kinase." (PMID 24834131, 2014).
Obesity (92 papers, 2012 to 2026). Accumulation of substantial excess body fat. "Although fat mass and basal metabolic rate cannot be equated with obesity, bias in the causal association between MAPK3 and knee OA should still be considered." (PMID 38540773, 2024). "Studies have discovered that specific polyphenols (such as quercetin and kaempferol) in whole green jackfruit powder can improve insulin resistance and lipid metabolism disorders by inhibiting the overactivation of MAPK3, providing a novel target for dietary intervention in obesity‐associated T2DM." (PMID 41503916, 2026). "Prior research has demonstrated that Leptin, Protocatechuic Acid, and other molecules can combat obesity and atherosclerosis through MAPK3/ERK1." (PMID 38246999, 2024). "Studies have shown that MAPK3 plays a critical role in adipocyte differentiation and obesity and can regulate the formation of fat." (PMID 35879730, 2022). "Previous reports indicated that MAPK1 contributes to the elevated secretion of monocyte chemoattractant protein-1 (MCP-1), and MAPK3 is associated with enhanced mRNA levels of inflammatory markers, such as CCL2, IL1β, and TNF-α in obesity." (PMID 34360840, 2021). "Mapk1 and Mapk3 (Erk2, Erk1 respectively) are integral mediators of inflammatory signal transduction that are central to obesity." (PMID 22384159, 2012). "Due to the fact that human MAPK3 is a common target for both obesity and DM, and is linked with the insulin signaling pathway, we report the virtual screening of the JME phytocompounds as novel potential inhibitors of human MAPK3 in this work." (PMID 36716329, 2023). "The downregulation of Mapk3, is concordant with a previous study in which mice lacking Mapk3 showed less adiposity and did not develop obesity or IR with an HFD." (PMID 40211057, 2025). "miR-148a might modulate fat deposition by targeting MAPKAPK5, MAPK3, and MAP2K2, and miR-148 has been shown to affect obesity and modulates adipocyte differentiation." (PMID 28293627, 2017).
non-small cell lung carcinoma (91 papers, 2004 to 2025). A group of at least three distinct histological types of lung cancer, including non-small cell squamous cell carcinoma, adenocarcinoma, and large cell carcinoma. "This, in turn, inhibits the mitogen-activated protein kinase 3/Nuclear factor kappaB cells (MAPK3/NF-κB) signaling pathway, suppressing the proliferation of non-small cell lung cancer (NSCLC) cells." (PMID 41399412, 2025).
bladder cancer (82 papers, 2010 to 2025). "In this study, we analyzed the gene expression of a Schistosoma hematobium specific microRNA “Sha-miR-71a” and mitogen-associated protein kinase-3 (MAPK-3) in the urine samples of 50 bladder cancer patients and 50 patients with benign bilharzial cystitis." (PMID 33139749, 2020). "Our results revealed that IHA is a reliable test in the diagnosis of bilharziasis associated with bladder cancer, and that Sha-miR-71a and MAPK-3 provide non-invasive specific biomarkers to diagnose BBC, as well as a potential role in testing bilharzial patients for risk to develop cancer." (PMID 33139749, 2020). "MAPK-3 gene was significantly expressed in the bladder cancer group, compared to bilharzial cystitis group." (PMID 33139749, 2020). "Within the bladder cancer group, transitional cell carcinoma cases had enhanced gene expression of Sha-miR-71a and MAPK-3 compared to those with squamous cell carcinoma." (PMID 33139749, 2020). "These hub nodes such as VEGFA, EGFR, ESR1, PLG, and MAPK3 were mainly enriched in pathways like proteoglycans in cancer, bladder cancer, and estrogen-signaling pathway." (PMID 32256653, 2020). "Pearson’s correlation analysis showed a strong correlation between Sha-miR-71a and its gene target MAPK-3 in both the bilharzial bladder cancer group and the bilharzial cystitis group." (PMID 33139749, 2020). "Within the bladder cancer group, transitional cell carcinoma cases had enhanced gene expression of MAPK-3 compared to those with squamous cell carcinoma, and cases with high-grade malignancy varied significantly in gene expression of MAPK-3 compared to those with low-grade malignancy." (PMID 33139749, 2020). "The KEGG bladder cancer pathway activation in poor prognosis CRCs was mostly due to increased expression of functional nodes HRAS/KRAS/NRAS, ARAF/BRAF/RAF1, MAPK1/MAPK3, and RPS6KA5." (PMID 36316649, 2022). "Urinary Sha-miR-71a & MAPK-3 revealed enhanced expression in BBC (p-value = 0.001) compared to non-bilharzial bladder cancer (NBBC) cases." (PMID 33139749, 2020). "In parallel, a similar analysis was performed for the expression levels of therespective central genes of these pathways: MAPK3 andMAPK1.For the individual gene level, only for bladder carcinoma did both genes showa consistent trend (were negative biomarkers) for both OS and PFS data." (PMID 40264578, 2025).
Insulin resistance (82 papers, 2009 to 2026). Increased resistance towards insulin, that is, diminished effectiveness of insulin in reducing blood glucose levels. "Integration of compound, target, and pathway data positioned IL-6 as a central mediator, interacting with MAPK1, MAPK3, MAPK14, PTGS2, and BCL2, genes associated with inflammation-induced insulin resistance and adipocyte dysfunction." (PMID 41382285, 2025). "Genome loci based data and population study support that highly connected genes, like ADIPOQ, MAPK3, PLCG1 and APPL1 in the database, play an important role in insulin resistance development." (PMID 29201145, 2017). "MAPK3 is a common target for T2DM, and evidence has shown that overactivation of MAPK3 can lead to insulin sensitivity impairment, while MAPK3 knockout can undo insulin resistance." (PMID 38903985, 2024). "Last but not least, approaches targeting MAPK3 (also known as extracellular signal-regulated kinase 1, ERK1) partially protect obese mice from insulin resistance and hepatic steatosis by decreasing adipose tissue inflammation and by increasing muscle glucose uptake." (PMID 33953784, 2021).
atherosclerosis (79 papers, 2009 to 2026). A disease characterized by the build-up of fatty material and calcium deposition in the arterial wall resulting in partial or complete occlusion of the arterial lumen. "By applying transcription analysis to study the Shexiang Baoxin pill (SBP) in atherosclerosis treatment, key target genes (MAPK3, AKT1, and STAT3) associated with the prescription’s efficacy were identified." (PMID 41282606, 2025). "MAPK1 and MAPK3 are serine/threonine kinases, and the expression of genes encoding these kinases is implicated in macrophage cholesterol homeostasis and atherosclerosis-related gene expression in a cell-based model of atherosclerosis." (PMID 33321972, 2020). "We found that Mapk3 is involved in many important signaling transduction pathways in atherosclerosis progression such as the Toll-like receptor, TGF-β, PI3K-Akt, MAPK, and mTOR signaling pathways." (PMID 31446617, 2019). "Also, it was previously reported that MAPK3A was differentially expressed in atherosclerosis, a common chronic vascular inflammatory disease, which suggested the potential role of MAPK3 in vascular injury." (PMID 36937538, 2023). "Our finding that GBH contains five core compounds (quercetin, kaempferol, baicalein, ellagic acid, and baicalin) that can be linked to six potential target genes (AKT1, CASP3, MAPK1, MAPK3, NOS2, and PTGS2) related to atherosclerosis is in agreement with previous reports." (PMID 33321972, 2020). "Classical MAPKs, including ERK1/2 (MAPK3/1), JNK1‐3 (MAPK8‐10), p38 (MAPK11‐14), and ERK5 (MAPK7), have been proven to be activated by shear stress and predominantly participate in atherosclerosis progression." (PMID 39763069, 2025). "Among these, pathways such as Lipid and atherosclerosis (hsa05417), the PI3K-Akt signaling pathway (hsa04151), and the AGE-RAGE signaling pathway in diabetic complications (hsa04933) were enriched by five key target genes (MAPK1, MAPK3, AKT1, PIK3R1, IL6)." (PMID 40170727, 2025). "Notably, ERK (Mapk1, Mapk3), IKBKB (Ikbkb), and NF-κB (Nfkb1) were included in Lipid and atherosclerosis." (PMID 40438398, 2025). "Three key pathways (pathways in cancer, the TNF signaling pathway, and lipid and atherosclerosis) and the top six anti-COVID-19 core targets (IL-6, PPARG, MAPK3, PTGS2, ICAM1, and MAPK1) were determined to be involved in the treatment of COVID-19 with active phytomolecules of Kochiae Fructus." (PMID 35992697, 2022).
ischemia (79 papers, 2004 to 2026). A hypoperfusion of the BLOOD through an organ or tissue caused by a PATHOLOGIC CONSTRICTION or obstruction of its BLOOD VESSELS, or an absence of BLOOD CIRCULATION. "There were 10 active constituents against ICVD, including quercetin, luteolin, kaempferol, and naringenin, and 10 important targets for anticerebral ischemia, namely, PIK3CA, APP, PIK3R1, MAPK1, MAPK3, AKT1, PRKCD, Fyn, RAC1, and NF-κB1." (PMID 35432563, 2022).